TPX2 (TPX2 microtubule nucleation factor)
Description:
Spindle assembly factor required for normal assembly of mitotic spindles. Required for normal assembly of microtubules during apoptosis. Required for chromatin and/or kinetochore dependent microtubule nucleation. Mediates AURKA localization to spindle microtubules. Activates AURKA by promoting its autophosphorylation at 'Thr-288' and protects this residue against dephosphorylation. TPX2 is inactivated upon binding to importin-alpha. At the onset of mitosis, GOLGA2 interacts with importin-alpha, liberating TPX2 from importin-alpha, allowing TPX2 to activate AURKA kinase and stimulate local microtubule nucleation.
Synonyms: DIL-2; p100; C20orf1; C20orf2; DIL2; HCA519; FLS353; GD:C20orf1; HCTP4; REPP86
Tractability: Small molecule: a structure with a bound ligand is known; a high-quality ligand is known. PROTAC: UniProt records ubiquitination sites on it; ubiquitination databases record sites on it; its protein half-life has been measured.
Gene: Protein-coding gene on chromosome 20 (31,739,248 to 31,801,805, forward strand). Ensembl gene ENSG00000088325.
Subcellular location: Nucleus; Cytoplasm, cytoskeleton, spindle; Cytoplasm, cytoskeleton, spindle pole
Subcellular location (Human Protein Atlas): Nucleoplasm; Cytokinetic bridge; Mitotic spindle
Pathways (Reactome):
Cell Cycle: AURKA Activation by TPX2
Gene Ontology:
Molecular function: importin-alpha family protein binding; molecular adaptor activity; protein binding; protein kinase binding; protein serine/threonine kinase activator activity
Biological process: activation of protein kinase activity; microtubule nucleation; mitotic spindle assembly; negative regulation of microtubule depolymerization; mitotic cell cycle; regulation of mitotic spindle organization
Cellular component: intercellular bridge; microtubule cytoskeleton; mitotic spindle; nucleoplasm; nucleus; spindle; spindle pole; cytosol; axon hillock; microtubule
Genetic constraint (gnomAD): Loss-of-function variants: 18 observed, 92.15 expected, observed/expected ratio (o/e) 0.2, 90% interval 0.13 to 0.29. The upper end of that interval is the gene's LOEUF score, 0.29, which puts it in group 1 of 6, group 1 being the genes least tolerant of losing a copy. Missense variants: 770 observed, 891.71 expected, observed/expected ratio (o/e) 0.86, 90% interval 0.81 to 0.92. Synonymous variants: 278 observed, 307.92 expected, observed/expected ratio (o/e) 0.9, 90% interval 0.82 to 1.
Homologues: Orthologues: chimpanzee TPX2 (95% identical), macaque TPX2 (94% identical), rabbit TPX2 (89% identical), dog TPX2 (87% identical), guinea pig TPX2 (84% identical), rat Tpx2 (80% identical), mouse Tpx2 (80% identical), pig TPX2 (78% identical), tropical clawed frog tpx2 (48% identical), zebrafish tpx2 (47% identical).
Diseases named in the same sentence as TPX2 in open-access papers:
TPX2 is named in the same sentence as 117 diseases in open-access papers, as found by Europe PMC text mining. Sharing a sentence is not in itself a finding about the gene and the disease. The quoted sentences say what the papers report.
breast cancer (58 papers, 2008 to 2026). A primary or metastatic malignant neoplasm involving the breast. "In breast cancer, TPX2 overexpression has been linked to heightened sensitivity to a c-Src inhibitor, dasatinib, through activation of the Yes-associated protein 1 (YAP) signaling pathway." (PMID 40362354, 2025). "A recent study on breast cancer samples, while confirming the association of high levels of TPX2 with chromosomal imbalances, challenges the value of TPX2 as an independent predictor of CIN." (PMID 39195284, 2024). "TPX2 was found in in silico studies to be related to the risk of the distant metastasis of breast cancers." (PMID 35806060, 2022). "IHC for TPX2 was then performed on three TMA slides collectively representing 253 patient-derived primary breast cancers with linked pathological and clinical parameters." (PMID 33622270, 2021). "Genes (G1) with high node centrality values in Basal II, such as HJURP and TPX2 have been linked to aberrant proliferation networks, cell invasion and metastasis in breast cancer, in line with the definition of BL1." (PMID 28351365, 2017). "Tpx2 is however, causally associated with metastatic progression in a model of human ER+ breast cancer." (PMID 25368990, 2014). "A module that was enriched for cellular proliferation genes, centered on the microtubule-associated gene TPX2 was found to be prognostic for estrogen receptor-positive (ER+) breast cancer." (PMID 25368990, 2014). "Known breast cancer susceptibility genes like TPX2, AURKA, TK1 and BIRC5 are among the top 7 global drivers (the other 3 top drivers are GINS2, COX4NB and NUP93)." (PMID 21806811, 2011). "However, the role and underlying functions of TPX2 in the progression and immunology of breast cancer is still vague." (PMID 38643462, 2024). "TPX2 can also be a therapeutic target for breast cancer and is associated with patient prognosis." (PMID 36202977, 2022). "A large network analysis of gene expression profiles derived from two large human breast cancer cohorts and multiple mouse models of metastatic disease identified a conserved genetic signature involving TPX2 which was associated with distant metastases and worse survival." (PMID 33622270, 2021). "In addition, 5 hub genes, CCNB2, FBXO5, KIF4A, MCM10, and TPX2 were identified and validated to be associated with the progression and worse prognosis of breast cancer." (PMID 30254986, 2018). "Also involved in the mitotic spindle assembly, TPX2, when over-expressed, has been associated with proliferation networks and metastasis enhancement, holding a prognostic value for breast cancer patients." (PMID 28351365, 2017). "Both 6DT1 and Mvt1 are derived from mouse genetically engineered models that are thought to be representative of human luminal breast cancers so if Tpx2 is mechanistically associated in metastatic disease one might expect similar results across multiple cell lines." (PMID 25368990, 2014). "We investigated the effects of ATC12 in 2D cultures and 3D mammospheres of breast cancer cell lines, as well as in patient-derived organoids, and observed an impairment of Aurora-A/TPX2 interaction and a decrease in cell viability and proliferation." (PMID 41876446, 2026). "All in all, we are trying to explore the mechanism of TPX2 on immune cells in breast cancer, which will be the direction and focus of our future efforts, aiming for exploring more powerful strategies targeting breast cancer patients." (PMID 38643462, 2024).
breast cancer (continued). "Univariate and multivariate Cox analyses of the correlation of TPX2 expression with overall survival (OS) among breast cancer patients." (PMID 38643462, 2024). "Extensive studies have revealed that TPX2 is upregulated and related to poor prognosis in multiple solid tumors, such as breast cancer and hepatocellular carcinoma." (PMID 38315450, 2024). "Then, we selected a representative breast cancer cell line MDA-MB-231 commonly used for research to testify the positive regulation between TPX2 and PD-L1 using flow cytometry and RT-QPCR methods." (PMID 38643462, 2024). "Increased expression of TPX2 has been found in some malignancies, such as esophageal cancer, colon cancer and breast cancer." (PMID 38466034, 2024). "Similar to the high TPX2 expressing breast cancer cells, line scan analysis of the TPX2/tubulin intensity ratio showed that high MYC Hela cells recruited increased levels of TPX2 along the length of the spindle." (PMID 38660563, 2024). "First, the correlation between TPX2 gene expression data and protein levels was confirmed in a cohort of primary breast cancer samples." (PMID 39195284, 2024). "The expression of TPX2 is related to the phosphorylation of Akt in a variety of malignant tumors, such as liver, ovarian, and breast cancers." (PMID 38466034, 2024). "Aiming to conduct a comprehensive analysis on the role of TPX2 in BRCA, we compared the expression of TPX2 in tumor and matched normal samples by GEO and TCGA datasets, suggesting that TPX2 was overexpressed in breast cancer." (PMID 38643462, 2024). "AURK and TPX2 have previously been identified as prognostic biomarkers of breast cancer patient survival." (PMID 37835564, 2023). "A cancer dependency map (depmap.org) further highlighted KIF11, AURKB, RACGAP1 and TPX2 as genes with essential effects in 47 breast cancer cell lines." (PMID 37835564, 2023). "For example, elevating TPX2 expression facilitates the development of breast cancer, and elevating the expression of H2AFZ promotes the development of hepatocellular carcinoma." (PMID 37059591, 2023). "For example, upregulated expression of TPX2 enhances breast cancer metastasis by mediating MMP2 and MMP9 expression." (PMID 36225568, 2022). "An overexpression of TPX2 has been highlighted in several malignancies, including breast cancer, pancreatic cancer and hepatocellular carcinoma." (PMID 36140359, 2022). "Several studies have demonstrated that TPX2 also played an important role in the development of prostate cancer, non‐small cell lung cancer, and breast cancer." (PMID 35778922, 2022). "A high level of TPX2 has been detected in several kinds of human cancer, such as bladder cancer, breast cancer, HCC, and especially prostate cancer." (PMID 34123781, 2021). "Nevertheless, this is a large study directly comparing well-localized TPX2 expression with outcomes and clinicopathologic parameters in a well-characterized cohort of breast cancer subjects with long-term follow up." (PMID 33622270, 2021). "Here we perform TPX2 IHC on a cohort of 253 patient-derived breast cancers and correlate these findings with available clinical, pathological, and molecular findings." (PMID 33622270, 2021). "In this study, we sought to compare TPX2 protein expression levels to a broad set of clinicopathologic parameters in a large patient-derived cohort of primary breast cancers." (PMID 33622270, 2021). "Recent database publications demonstrated the possible mechanisms of miR-491-5p in suppressing the migration and invasion of breast cancer by targeting ZNF-703 to regulate the AKT/mTOR pathway or via TPX2 targeting." (PMID 34395516, 2021).
breast cancer (continued). "We and others have shown that TPX2 mRNA transcripts are the most predictive of CIN in breast cancers and other solid malignancies." (PMID 33622270, 2021). "We perform TPX2 IHC on a cohort of 253 primary breast cancers and adopt a clinically amenable scoring system to separate tumors into low, intermediate, or high TPX2 expression." (PMID 33622270, 2021). "In breast cancer cells, TPX2 affects cancer cell colony formation, proliferation, and invasion through PI3K/AKT signal pathway and promotes tumor progression." (PMID 32766313, 2020). "According to the PPI networks, five hub genes (TPX2, KIF2C, CDCA8, BUB1B, and CCNA2) were identified as key genes associated with breast cancer progression." (PMID 31285741, 2019). "Five hub genes, including TPX2, KIF2C, CDCA8, BUB1B, and CCNA2, were validated to be notably associated with the shorter DMFS of breast cancer in the patient cohort based on KM Plotter." (PMID 31285741, 2019). "In breast cancer cells, TPX2 promotes cancer cell invasion and migration via regulating MMP2 and MMP9 expression." (PMID 31285741, 2019). "Overall, we identified five genes (TPX2, KIF2C, CDCA8, BUB1B, and CCNA2) associated with distant metastasis, indicating these genes as potential biomarkers for assessing the risk of breast cancer recurrence and distant metastasis." (PMID 31285741, 2019). "The different phenotype of Tpx2 knockdown in the 6DT1 and Mvt1 mammary cell lines does raise the possibility that the results observed here cannot be generalized across all breast cancers." (PMID 25368990, 2014). "Tpx2, the most highly connected gene within a proliferation network specifically prognostic for estrogen receptor positive (ER+) breast cancers, enhances metastatic disease, but in a tumor autonomous, proliferation-independent manner." (PMID 25368990, 2014). "Previously TPX2 was identified as the most highly connected node in a gene network that predicted distant metastasis free survival (DMFS) in ER+ breast cancers." (PMID 25368990, 2014). "In summary, we validated the Tpx2 gene previously identified through cross species gene expression network analysis as a regulator of breast cancer metastasis." (PMID 25368990, 2014). "We acquired further evidence that tumor autonomous mechanisms provide important determinants of metastatic potential in ER+ mammary carcinomas and showed that Tpx2 can regulate metastasis independently of proliferation." (PMID 25368990, 2014). "SOX11 and TPX2 showed consistent upregulation of twofold or greater in PR- breast cancers across datasets." (PMID 23506684, 2013). "Moreover, we compared the gene expression difference of TPX2 in breast cancer cells and normal breast cell and found that TPX2 was higher expressed in breast cancer." (PMID 38643462, 2024). "Besides, high TPX2 expression was related to poor prognosis in various tumors, including pancreatic cancer, breast cancer, lung cancer, etc.." (PMID 38643462, 2024). "Thus, this study attempted to explore the functional effect of TPX2 on modulating PD-L1 expression in breast cancer." (PMID 38643462, 2024). "We propose that future studies examine whether low TPX2 nuclear expression is predictive of radiation response in breast cancer." (PMID 33622270, 2021).
breast cancer (continued). "In breast cancers, TPX2 mRNA levels have been reported as a strong predictor of aggressive behavior, reduced response to therapy, and poor survival, while depletion of TPX2 can suppress proliferation and promote apoptosis." (PMID 33622270, 2021). "Importantly, TPX2 was also described as prognostic biomarker in gynecological cancer such as breast cancer or ovarian cancer." (PMID 34680205, 2021). "Numerous studies have identified TPX2 RNA levels as broadly predictive of aggressive behavior, reduced response to therapy, and poor survival across multiple solid malignancies, including breast cancer." (PMID 33622270, 2021). "CDC20 could be considered as a potential predictive indicator for prognosis of breast cancer with co-expressed TPX2 gene." (PMID 32285914, 2020). "While the HMMR association study in BRCA1/2 mutation carriers drew on a partial dataset from the Consortium of Investigators of Modifiers of BRCA1/2 (CIMBA), the depicted mechanistic model highlighted additional gene candidates for breast cancer risk; i.e., AURKA, TPX2, and TUBG1." (PMID 25830658, 2015). "It thus appears that in the 6DT1 mammary carcinoma cells, Tpx2 functionally contributes to metastasis through an unknown mechanism, but independent of cell proliferation or EMT." (PMID 25368990, 2014). "They observed that, in BRCA2-deficient breast cancer cells, the silencing of either AurkA or TPX2 causes a reduction in cell viability compared to BRCA2-proficient cells, suggesting that the survival of genomically unstable cancer cells depends on the AurkA/TPX2 signalling axis." (PMID 39195284, 2024). "Interestingly, both AURKA and TPX2 are included in this minimal signature, which directly correlates with an increased DNA index (aneuploidy vs. euploidy) in samples from breast cancer patients, and is able to stratify grade 2 tumours for a good or bad prognosis." (PMID 39195284, 2024). "TPX2 is overexpressed in esophageal cancer, colorectal cancer, hepatocellular carcinoma, colon cancer, bladder cancer, clear cell renal carcinoma, pancreatic cancer, ovarian carcinoma, breast cancer, and neuroblastoma, and its degree of expression has been associated with poor prognoses." (PMID 36304254, 2022). "Further, TPX2 siRNA inhibits tumor cell invasion and metastasis promotes tumor cell death, and could be a potential treatment option for esophageal carcinoma, medullary thyroid carcinoma, colon cancer, and breast cancer." (PMID 36304254, 2022). "Five hub genes (TPX2, KIF2C, CDCA8, BUB1B, and CCNA2) associated with the risk of distant metastasis were extracted for further research, which might be used as biomarkers to predict distant metastasis of breast cancer." (PMID 31285741, 2019). "Of note, knockdown of Tpx2 in Mvt1 mammary carcinoma cells impaired both primary tumor growth and pulmonary metastasis (data not shown), suggesting that in this context the known mitosis-related function of Tpx2 may be more critical." (PMID 25368990, 2014). "It was seen through different databases that HMMR was highly upregulated in various malignancies, including breast cancer, and HMMR has a correlation with AURKA, TPX2, and CDK1, which are also involved in the upregulation of mTOR signaling pathways." (PMID 38576486, 2024). "Results revealed that KIF11, AURKB, TPX2 and KIFC1 are essential genes whose depletion in both breast cancer cell lines impacts cell viability." (PMID 37835564, 2023). "TPX2 is overexpressed in a variety of malignant tumor tissues, including HCC, colon cancer, breast cancer, esophageal cancer, and cervical cancer." (PMID 37240068, 2023).